RNU6-845P (RNA, U6 small nuclear 845, pseudogene)
Gene: Small nuclear RNA gene on chromosome 16 (46,556,089 to 46,556,191, reverse strand). Ensembl gene ENSG00000199448.
Homologues: Orthologues: chimpanzee U6 (99% identical), macaque U6 (94% identical), dog U6 (83% identical), pig U6 (82% identical), guinea pig U6 (77% identical), rabbit U6 (76% identical). Paralogues in human: RNU6-1318P (87% identical), RNU6-345P (86% identical), RNU6-86P (85% identical), RNU6-38P (84% identical), RNU6-413P (84% identical), RNU6-467P (84% identical), RNU6-698P (84% identical), RNU6-774P (84% identical), RNU6-890P (84% identical), RNU6-28P (83% identical), RNU6-405P (83% identical), RNU6-433P (83% identical), and 1286 more.